CMAHP (cytidine monophospho-N-acetylneuraminic acid hydroxylase, pseudogene )
Synonyms: CMAH; CSAH
Gene: Long non-coding RNA gene on chromosome 6 (25,061,611 to 25,452,263, reverse strand). Ensembl gene ENSG00000293489.
Diseases named in the same sentence as CMAHP in open-access papers:
CMAHP is named in the same sentence as 16 diseases in open-access papers, as found by Europe PMC text mining. Sharing a sentence is not in itself a finding about the gene and the disease. The quoted sentences say what the papers report.
gastric cancer (2 papers, 2022 to 2023). A primary or metastatic malignant neoplasm involving the stomach. "Similarly, CMAHP promotes gastric cancer metastasis formation by reducing the ubiquitination of Snail." (PMID 36348434, 2022).
clear cell renal cell carcinoma (1 paper, 2021). "Different from CMAHP, higher expression of unitary pseudogene CPHL1P was associated with worse patient OS (log-rank test, p = 4.98 × 10-6) in clear cell renal cell carcinoma (KIRC) and worse patient RFS (log-rank test, p = 0.00245) in prostate cancer (PRAD), respectively." (PMID 34425866, 2021).
cutaneous melanoma (1 paper, 2021). A primary melanoma arising from atypical melanocytes in the skin. "Higher CMAHP expression was associated with better patient OS in lung adenocarcinoma (LUAD, log-rank test, p = 0.00142)) and cutaneous melanoma (SKCM, log-rank test, p = 7.47 × 10−6), respectively." (PMID 34425866, 2021).
leukemia (1 paper, 2020). A malignant (clonal) hematologic disorder, involving hematopoietic stem cells and characterized by the presence of primitive or atypical myeloid or lymphoid cells in the bone marrow and the blood. "Among them, only CMAHP was reported to be related to MLL-positive AML, and other lncRNAs have not been reported in leukemia." (PMID 32850463, 2020).
tumor (1 paper, 2023). "The CMAHP mRNA expression in the anti‐NeuGc Ab‐positive group was also significantly higher in the tumor tissues than in the normal tissues." (PMID 37265054, 2023). "The NeuGc Ag‐positive group exhibited a significantly higher CMAHP mRNA expression in the tumor tissues than that in the normal tissues (P < .05)." (PMID 37265054, 2023). "CMAHP mRNA expression was significantly higher in the tumor tissues of the NeuGc Ag‐positive group than in the normal tissues (P < .05)." (PMID 37265054, 2023). "To address this possibility, we evaluated CMAHP mRNA expression normalized against β‐actin in the normal and tumor portions of the resected liver tissues from the hepatectomized HCC patients (n = 100)." (PMID 37265054, 2023). "RT‐qPCR results revealed that the tumor tissues exhibited significantly higher CMAHP mRNA expression than the normal tissues (P < .01)." (PMID 37265054, 2023).
CMAHP also shares sentences with these, for which no sentence is quoted: Cognitive impairment (2 papers); cognitive decline (1); Glucose intolerance (1); Hyperglycemia (1); infarction (1); ischemic stroke (1); lung adenocarcinoma (1); malaria (1); Metabolic Disorders (1); prostate carcinoma (1); Type II diabetes (1).